DLG1 (discs large MAGUK scaffold protein 1)
Description:
Essential multidomain scaffolding protein required for normal development (By similarity). Recruits channels, receptors and signaling molecules to discrete plasma membrane domains in polarized cells. Promotes epithelial cell layer barrier function via maintaining cell-cell adhesion (By similarity). May also play a role in adherens junction assembly, signal transduction, cell proliferation, synaptogenesis and lymphocyte activation. Regulates the excitability of cardiac myocytes by modulating the functional expression of Kv4 channels. Functional regulator of Kv1.5 channel. During long-term depression in hippocampal neurons, it recruits ADAM10 to the plasma membrane.
Synonyms: SAP-97; SAP97; hdlg; DLGH1; dJ1061C18.1.1
Tractability: Small molecule: a structure with a bound ligand is known. Antibody: UniProt places it where antibodies can reach, with high confidence; its Gene Ontology location is reachable by antibodies, with high confidence. PROTAC: UniProt records ubiquitination sites on it; ubiquitination databases record sites on it; its protein half-life has been measured.
Gene: Protein-coding gene on chromosome 3 (197,042,560 to 197,299,330, reverse strand). Ensembl gene ENSG00000075711.
Subcellular location: Cell membrane; Basolateral cell membrane; Endoplasmic reticulum membrane; Postsynaptic density; Synapse; Cell membrane, sarcolemma; Apical cell membrane; Cell junction; Cytoplasm
Subcellular location (Human Protein Atlas): Vesicles; Basal body; Plasma membrane
Pathways (Reactome):
Neuronal System: Activation of Ca-permeable Kainate Receptor; Assembly and cell surface presentation of NMDA receptors; Long-term potentiation; Negative regulation of NMDA receptor-mediated neuronal transmission; Ras activation upon Ca2+ influx through NMDA receptor; Synaptic adhesion-like molecules; Trafficking of AMPA receptors; Unblocking of NMDA receptors, glutamate binding and activation
Developmental Biology: NrCAM interactions
Signal Transduction: RAF/MAP kinase cascade
Gene Ontology:
Molecular function: cadherin binding; kinase binding; L27 domain binding; phosphatase binding; potassium channel regulator activity; protein binding; transmembrane transporter binding; cytoskeletal protein binding; GMP kinase activity; ionotropic glutamate receptor binding; phosphoprotein phosphatase activity; protein kinase binding; molecular adaptor activity; structural constituent of postsynaptic density
Biological process: actin filament organization; astral microtubule organization; bicellular tight junction assembly; cell-cell adhesion; cortical actin cytoskeleton organization; cortical microtubule organization; endothelial cell proliferation; establishment of centrosome localization; negative regulation of ERK1 and ERK2 cascade; negative regulation of G1/S transition of mitotic cell cycle; negative regulation of p38MAPK cascade; negative regulation of transcription by RNA polymerase II; positive regulation of potassium ion transport; positive regulation of protein localization to plasma membrane; protein localization to plasma membrane; protein-containing complex localization; regulation of cell shape; regulation of membrane potential; regulation of non-canonical NF-kappaB signal transduction; regulation of protein localization to synapse; chemical synaptic transmission; establishment or maintenance of cell polarity; establishment or maintenance of epithelial cell apical/basal polarity; membrane repolarization during ventricular cardiac muscle cell action potential; nervous system development; and 16 more
Cellular component: anchoring junction; apical plasma membrane; basolateral plasma membrane; bicellular tight junction; cell junction; cell-cell junction; cytoplasm; cytoplasmic side of plasma membrane; endoplasmic reticulum; extracellular exosome; Golgi apparatus; immunological synapse; microtubule; MPP7-DLG1-LIN7 complex; nucleus; perinuclear region of cytoplasm; plasma membrane; synaptic membrane; adherens junction; cytosol; endoplasmic reticulum membrane; intercalated disc; neuromuscular junction; neuron projection; postsynaptic density; and 11 more
Genetic constraint (gnomAD): Loss-of-function variants: 18 observed, 54.37 expected, observed/expected ratio (o/e) 0.33, 90% interval 0.23 to 0.49. The upper end of that interval is the gene's LOEUF score, 0.49, which puts it in group 2 of 6, group 1 being the genes least tolerant of losing a copy. Missense variants: 526 observed, 632.49 expected, observed/expected ratio (o/e) 0.83, 90% interval 0.77 to 0.89. Synonymous variants: 175 observed, 209 expected, observed/expected ratio (o/e) 0.84, 90% interval 0.74 to 0.95.
Homologues: Orthologues: chimpanzee DLG1 (99% identical), macaque DLG1 (99% identical), dog DLG1 (99% identical), rabbit DLG1 (98% identical), pig DLG1 (98% identical), mouse Dlg1 (97% identical), rat Dlg1 (96% identical), guinea pig DLG1 (94% identical), tropical clawed frog dlg1 (87% identical), zebrafish dlg1b (72% identical). Paralogues in human: DLG2 (72% identical), DLG4 (60% identical), DLG3 (60% identical).
Diseases named in the same sentence as DLG1 in open-access papers:
DLG1 is named in the same sentence as 112 diseases in open-access papers, as found by Europe PMC text mining. Sharing a sentence is not in itself a finding about the gene and the disease. The quoted sentences say what the papers report.
schizophrenia (24 papers, 2010 to 2025). A major psychotic disorder characterized by abnormalities in the perception or expression of reality. "The human discs, large homolog 1 gene (DLG1) is mapped to the schizophrenia-susceptibility locus 3q29, and it encodes a scaffold protein that interacts with the N-methyl-D-aspartate receptor presumably dysregulated in schizophrenia." (PMID 26440542, 2015). "In the present study, we have newly isolated a splicing variant, 3b(+) mRNA, of the human DLG1 gene that is mapped to chromosome 3q29, a schizophrenia-susceptibility locus, in humans." (PMID 26440542, 2015). "In neurological contexts, different mutations (including microdeletions, microduplications, methylation changes and single-nucleotide variants) that result in a DLG1 deficiency have been shown in schizophrenia, autism, Parkinson’s disease, epilepsy and cerebral palsy." (PMID 37422595, 2023). "Because all the subjects with early-onset schizophrenia in the current study possess the T/T genotype, the reduced level of the DLG1 3b(+) transcript may be involved in the susceptibility and/or pathophysiology of early-onset schizophrenia." (PMID 26440542, 2015). "Furthermore, and more specifically, a recent study has found an association between some SNPs inside the DLG1 gene and males with schizophrenia." (PMID 20967226, 2010). "To date, neither gene is known to be causative of any disease; however, DLG1 has been associated with cleft-lip/palate and depression, and DLG2 has been associated with schizophrenia and renal oncocytoma." (PMID 37422595, 2023). "The DLG family members, DLG1 and DLG2, which also interact with DLGAPs and NMDA receptors have been linked to schizophrenia as well." (PMID 28870203, 2017). "In this study, we first performed family-based association analysis of genetic variants in the PSD genes; DLG4, DLG1, PICK1 and MDM2 using Japanese schizophrenia pedigrees." (PMID 23936182, 2013). "By performing a three staged genetic analysis in independent cohorts of Japanese and Chinese schizophrenia patients, our study aimed to investigate the role of genomic variants in DLG4, DLG1, PICK1 and MDM2 in determining the predisposition to schizophrenia." (PMID 23936182, 2013). "In the present study, to extend our insight into the pathophysiological role of the DLG1 gene in schizophrenia, we first explored the complementary DNA (cDNA) library of the post-mortem human cerebral cortex in an attempt to identify unreported DLG1 splicing variants." (PMID 26440542, 2015). "None of the patients carried the intronic variant rs3915512, which has previously been associated with reduced cortical expression of a splicing variant in DLG1 in patients with nonearly‐onset schizophrenia, and with neurocognitive function in schizophrenia in general." (PMID 31347308, 2019). "The link of DLG1, DLG2 and DLG4 to schizophrenia has been well documented." (PMID 28870203, 2017). "Moreover, the expression level of DLG1 and DLG2 was also found to be significantly skewed in a schizophrenia rat model and in schizophrenic patients." (PMID 28870203, 2017).
cervical carcinoma (14 papers, 2011 to 2025). A carcinoma arising from either the exocervical squamous epithelium or the endocervical glandular epithelium. "The degradation of Dlg1 by HPV16 E6 is relevant to the loss of gap junctional communication in cervical cancer, as the N- and C-termini of Dlg1 have been shown to interact directly with the Cx43 C-terminus, providing E6 with the ability to target Cx43 through Dlg1." (PMID 39522757, 2024). "However, subsequent studies demonstrated that such degradation may be incomplete because significant levels of DLG1 were still detectable in HPV-associated cervical cancer cell lines." (PMID 32264889, 2020). "First, using HPV-18-positive cervical cancer cells, edited in the CKII phospho-acceptor site of E7, we found that the genetic mutation of this site is linked to less abundant endogenous DLG1." (PMID 36153517, 2022). "The results of several studies investigating DLG1 function in cervical cancer development suggest that its expression and localization varies in HPV-associated lesions, probably due to the combined action of the viral oncoproteins E6 and E7." (PMID 34503271, 2021). "In summary, this study constitutes a step forward in the knowledge of how DLG1 expression is deregulated during cervical cancer development and the involvement of the HPV oncoproteins in such alteration." (PMID 32264889, 2020). "In HPV16-positive cervical cancer cells, RhoG activity is upregulated and E6 contributes to this upregulation by forming a complex with DLG1 and a RhoG guanine exchange factor (SGEF)." (PMID 26797638, 2016). "As there was partial colocalisation with a marker of the lysosomes and siRNA knockdown of Dlg1 further lowered Cx43 levels in cervical cancer cells, it was proposed that Dlg1 may maintain a pool of Cx43 in the cytoplasm and protect it from degradation." (PMID 39522757, 2024). "However, subsequent studies showed significant levels of DLG1 in HPV-positive cervical cancer cell lines, indicating that E6-mediated degradation of DLG1 is incomplete." (PMID 36153517, 2022). "For this, we analysed DLG1 levels in the cervical carcinoma C4-1 cells, which bear a single copy of the HPV-18 genome, and in two derived cell lines (B8 and A15), that were generated by genome editing, introducing mutations into the 18E7 CKII site which prevent its phosphorylation." (PMID 36153517, 2022). "Taken together, these data suggest that DLG1 may play an important role in cervical cancer development." (PMID 34503271, 2021). "In invasive cervical carcinomas, the abundance of DLG1 was very low or almost undetectable." (PMID 32264889, 2020). "DLG1 is mainly identified as a tumor suppressor, since overexpression is observed early in the onset of cervical cancer (CeCa) and elevated DLG1 promotes intestinal tumorigenesis, predicts poor prognosis in people with CRC and increases the invasiveness of NSCLC cell lines." (PMID 32102656, 2020). "In metastatic cervical cancers, the reduction in expression of the polarity proteins DLG1 and SCRIB could be E6 mediated via the proteasome." (PMID 26797638, 2016). "Dlg1 is also the target of viral oncoproteins such the oncogenic human papillomavirus E6, which targets Dlg1 for destruction and may account for the low levels of Dlg1 observed in cervical cancers." (PMID 31289196, 2019). "Previously we have shown that Cx43 could be detected as binding to Dlg1 in a GST pulldown experiment in cervical cancer cells and that GST–Dlg1 could interact directly in vitro with FLAG-tagged Cx43." (PMID 37288673, 2023).
breast carcinoma (12 papers, 2011 to 2025). "Remarkably, the loss of DLG1 expression at cell to cell contact (normal localization), together with an increase in DLG1 levels and unusual cytoplasmic distribution, were also detected in biopsies derived from other tumours, like colon adenocarcinoma and breast cancer." (PMID 32264889, 2020). "To clarify the role of PBM in CLDN6 linking DLG1 to PBK, we transfected PBM-deficient CLDN6 in breast cancer cells." (PMID 39984471, 2025). "Although some mutations in the PDZ-2 domain of DLG1 have been found in breast cancer, there is still no clear explanation of their effects, if any, on tumor development and/or progression." (PMID 34503271, 2021). "This interaction, mediated by the carboxyl-terminal PBM of PTEN and PDZ domain 2 of Dlg1, enhances PTEN activity to block proliferation and viability of MCF-7 breast carcinoma cells and to suppress Schwann cell myelination of peripheral nerves." (PMID 24788832, 2014).
Parkinson disease (5 papers, 2013 to 2023). A progressive degenerative disorder of the central nervous system characterized by loss of dopamine producing neurons in the substantia nigra and the presence of Lewy bodies in the substantia nigra and locus coeruleus. "DLG1 and RPS4Y1 have been reported as distinct candidate genes or risk factors for early Parkinson's disease by analysis of gene expression in whole blood." (PMID 31487305, 2019). "To assess whether DLG1 and CAP2 transcript alterations were selective for SCZ, we also measured their expression in the superior frontal gyrus of patients affected by neurodegenerative disorders, like Parkinson’s and Alzheimer’s disease." (PMID 35163460, 2022).
viral infection (4 papers, 2012 to 2023). "Indeed, PBM association with Scribble and Dlg1 promotes virus infection." (PMID 36082118, 2022). "Since MAGI1 depletion robustly inhibits IAV infection, MAGI1's role in supporting virus infection is larger than that of Scribble and Dlg1." (PMID 36082118, 2022). "This novel mechanism of PI3K activation may serve as a paradigm to understand how other pathogenic human viruses dysregulate PI3K and how the common viral target Dlg1, and possibly other PDZ proteins, contributes to viral infections and diseases." (PMID 24788832, 2014). "Hence, studies of human adenovirus and its subversion of cellular PI3K, Dlg1, and other PDZ proteins may yield mechanistic insights that aid development of new therapeutic strategies for treating viral diseases in people." (PMID 24788832, 2014).
Arrhythmia (3 papers, 2017 to 2023). Any cardiac rhythm other than the normal sinus rhythm. "It is conceivable that this mutation could affect DLG1-Kv4.3 or DLG1-NaV1.5 interactions, modulating their functions and favoring susceptibility for arrhythmias." (PMID 28750076, 2017).
autism (3 papers, 2019 to 2023). Persistent deficits in social interaction and communication and interaction as well as a markedly restricted repertoire of activity and interest as well as repetitive patterns of behavior.
Brugada syndrome (3 papers, 2017 to 2025). A genetically heterogeneous condition characterized by complete or incomplete right bundle branch block accompanied by ST elevation in leads V1-V3. "We report in a large multigenerational family with Brugada syndrome a novel DLG1 gene variant that was associated with typical electrocardiographic presentation and heterogenous cardiac phenotype." (PMID 36833354, 2023). "A DLG1 gene variant was identified to be associated with Brugada syndrome." (PMID 36833354, 2023). "Both channels are implicated in Brugada syndrome (BRGDA1, OMIM: 601144; BRGDA9, OMIM: 616399), and consequently a DLG1 variant may confer susceptibility to arrhythmias as demonstrated by a putative DLG1 pathogenic mutation in a patient affected by this syndrome." (PMID 28750076, 2017).
cervical tumour (3 papers, 2012 to 2023). "Previously, we have demonstrated that Cx43 can bind Dlg1 in human papillomavirus (HPV)-positive cervical tumour cells." (PMID 37288673, 2023). "Our previous studies have demonstrated that Cx43 and Dlg1 can interact in human papillomavirus type 16 (HPV16)-positive cervical tumour cells." (PMID 37288673, 2023). "The human papillomavirus E6 oncoprotein binds the central PDZ domain of Dlg1 and can target it for proteasomal degradation, and we showed that a three-way complex of Cx43–Dlg1–E6 was present in cervical tumour cells." (PMID 37288673, 2023).
cleft palate (3 papers, 2012 to 2019). Cleft palate is a fissure type embryopathy that affects the soft and hard palate to varying degrees. "In fact, several of the Shh target genes identified here in the cNCC, including Adamts9, Edn1, Dlg1, and Efnb1, are already implicated in cleft palate pathogenesis by existing mouse models." (PMID 29945554, 2018). "DLG1 null mutant mice die soon after birth and exhibit major congenital birth defects with craniofacial dysmorphogenesis including cleft palate." (PMID 31652620, 2019). "Since mice that are germline deficient for dlg1 develop abnormally and exhibit perinatal lethality due to cleft palate and the inability to suckle, both mouse models containing a dlg1 germline deletion were maintained and bred as heterozygotes." (PMID 23028902, 2012).
colon adenocarcinoma (3 papers, 2020 to 2021). "Interestingly, DLG1 protein levels are significantly lower in NSCLC and hepatocellular carcinoma (HCC) than in the corresponding normal tissues, but are nearly undetectable in poorly differentiated stages of colon adenocarcinoma, in contrast to our findings and the existing literature." (PMID 32102656, 2020).